ATF2 (activating transcription factor 2)
Diseases named in the same sentence as ATF2 in open-access papers (continued):
Sharing a sentence is not in itself a finding about the gene and the disease.
cervical cancer (6 papers, 2013 to 2024). A primary or metastatic malignant neoplasm involving the cervix. "In summary, this study found that MAP4K4 and WT1 contributed to SOX6‐induced cellular senescence in cervical cancer by synergistically activating the ATF2–TGFβ2–Smad2/3 signaling pathway." (PMID 38383842, 2024). "MAP4K4 and WT1 contribute to SOX6‐induced cellular senescence in cervical cancer by synergistically activating the ATF2–TGFβ2–Smad2/3 signaling pathway." (PMID 38383842, 2024). "In summary, miR-204 inhibits proliferation and autophagy and induces apoptosis in cervical cancer cells by targeting ATF2." (PMID 35456001, 2022). "They found that levels of miR-338 were decreased in cervical cancer tissues and cells, and inversely correlated with ATF2 protein levels, indicating that ATF2 is a direct target of miR-338." (PMID 35456001, 2022). "The results indicate that miR-338 may inhibit cell proliferation and autophagy by targeting the mTOR signaling pathway via ATF2 in cervical cancer cells." (PMID 35456001, 2022). "ATF2 was also identified as a target gene of miR-338-3p, and it could inhibit the proliferation of cervical cancer cells via targeting the PI3K/Akt/mTOR signaling cascade." (PMID 35765408, 2022). "In particular, seven genes showed higher expression in cervical cancer and positively correlated with EMT scores, including CSRP2BP, LPCAT1, NAT14, CREBBP, MSL3, ATF2 and GNPNAT1." (PMID 37845756, 2023). "In total, 28 genes (e.g., ATF2, BRCA2, CSRP2BP and EP300) were up-regulated and 16 genes (e.g., CDY1, CHAT and CRAT) were down-regulated in cervical cancer." (PMID 37845756, 2023).
colon cancer (6 papers, 2014 to 2023). "Low ATF2 expression is associated with worse prognosis in colon cancer (CC) patients and is characteristic of highly aggressive and invasive CC tumors." (PMID 37237279, 2023). "Another study reports that ATF2 can activate the expression of ATF3 in response to stress in colonic cancer cells." (PMID 25254641, 2014). "The top oncogenic signatures identified from male smoking include tumor suppressor genes (PTEN and RB1), colon cancer gene sets (CTIP and SNF5), skin tumor progression protein (ATF2), oncogenic signatures KRAS-600-LUNG and E2F3 pathway genes." (PMID 25621181, 2014). "Silencing of ATF2 revealed downregulation of PLOD2, HADH, LCOR and REEP1 mRNA expression; thus suggesting ATF2 as the transcription factor in non-canonical Wnt signaling in colon cancer cells." (PMID 29453334, 2018).
glioma (6 papers, 2015 to 2024). A benign or malignant brain and spinal cord tumor that arises from glial cells (astrocytes, oligodendrocytes, ependymal cells). "The network topology analysis performed in this study revealed a set of central nodes associated to glioma malignancy, such as Map3k14, Mapk1, Actn4, Hspa5, Atf2, Rac1,E2f1, Shc1, Pik3ca, Akt1, Vim and Egr1." (PMID 26582089, 2015). "Transcripts of VV-GMCSF-Lact-infected glioma and NB cells that directly correlate with CD50 are enriched with mRNAs controlled by transcription factors ATF2, BRCA1, CREB1, ELF1, TAF1, UBTF, and YY1." (PMID 37998351, 2023). "Moreover, ATF2 had recently been confirmed to directly interact with miR-622 (applying luciferase reporter activity assays) in non-HCC (i.e., glioma) cancer cells." (PMID 33803354, 2021).
Obesity (6 papers, 2014 to 2023). Accumulation of substantial excess body fat. "The sole transcription factor with binding sites enriched in Western diet-associated genes, ATF2, is a key mediator of inflammatory pathways and diseases, including response to bacterial endotoxin, atherosclerosis, and obesity." (PMID 34338633, 2021). "Evidence for p38-linked ATF2 signaling as a regulatory component in obesity-related inflammation may lend insight into the pathological effects of overnutrition." (PMID 25049453, 2014). "In vitro studies in human and mouse cell lines as well as knockout mice reveal the activation of ATF2 in several inflammatory diseases including obesity, hepatitis, inflammatory pain, and allergic asthma." (PMID 25049453, 2014). "ATF2 is a leucine zipper transcription factor with documented roles in inflammatory pathologies such as obesity, inflammation-induced pain, hepatitis, and asthma, and its known functions include transcriptional regulation of CAMs, proinflammatory cytokines, and chemokines." (PMID 32117236, 2020). "In adipose tissue, Sirt6 deletion moderates the binding of phosphorylated ATF2 to the PGC-1α promoter, which subsequently reduces the thermogenic programme in brown fat and eventually leads to obesity." (PMID 37582706, 2023). "As a repressor of the p38/MAPK pathway, TOB1 can suppress p38/MAPK signaling by decreasing phosphorylation of p38 and ATF2; p38/MAPK acts as an enhancer of adipogenesis contributes to obesity." (PMID 31118946, 2019). "Reports have demonstrated that ATF2 is highly expressed in infiltrating macrophages and may suppress ATF3 transcription in M1 macrophages of white adipose tissues in obesity." (PMID 25049453, 2014).
atherosclerosis (5 papers, 2021 to 2025). A disease characterized by the build-up of fatty material and calcium deposition in the arterial wall resulting in partial or complete occlusion of the arterial lumen. "In addition, HIF1A-AS2 aggravates inflammation in atherosclerosis by inducing Activating Transcription Factor 2 (ATF2)." (PMID 39273673, 2024).
bladder cancer (5 papers, 2020 to 2022). "Androgens have also been shown to activate ERK, as well as ATF2 which can be phosphorylated in response to phospho-ERK signals, in bladder cancer cells via the AR pathway." (PMID 33652650, 2021). "In AR-positive bladder cancer cells, DHT induced the expression of phospho-ATF2 and phospho-ERK as well as nuclear translocation and transcriptional activity of ATF2." (PMID 32759680, 2020). "Treatment with DHT in AR-positive bladder cancer cells induces the expression of p-ERK and also induces the expression of p-ATF2, but if any change in ATF2 protein expression is observed, these effects could be antagonized by HF." (PMID 33919565, 2021).
glioblastoma (5 papers, 2014 to 2024). The most malignant astrocytic tumor (WHO grade IV). "A study on glioblastoma cell lines also found miR-204 to affect migration and invasion, although due to interaction with ATF2 mRNA." (PMID 29382303, 2018). "In glioblastoma cells, TGFβ activates p38 MAPK and ATF2 but does not induce JNK phosphorylation; furthermore, inhibition of p38 MAPK decreases TGFβ-induced phosphorylation of ATF2 and Smad2." (PMID 24674138, 2014).
liver cancer (5 papers, 2021 to 2024). An epithelial or non-epithelial malignant neoplasm that arises from the liver. "In summary, this work confirmed that the high activity of JNK/c-Jun-ATF2/Galectin-1 mediates cisplatin resistance in liver cancer." (PMID 37215991, 2023). "Our study found that CDDP activated JNK and enhanced the formation of c-Jun-ATF2 in liver cancer cells, while the function-depleted c-Jun-ATF2 increased CDDP treatment efficacy." (PMID 37215991, 2023). "Our findings revealed that JNK/c-Jun-ATF2/Galectin-1 is a potential target to reverse CDDP resistance in liver cancer." (PMID 37215991, 2023). "Taken together, this work revealed that JNK/c-Jun-ATF2/Galectin-1 is a valuable target to overcome CDDP resistance in liver cancer and proposed a feasible approach to trace JNK activity in vivo." (PMID 37215991, 2023). "More interestingly, the formation of c-Jun-ATF2 heterodimer increased when liver cancer cells were treated with CDDP." (PMID 37215991, 2023). "A total of 92 genes overlapped between the targets of c-Jun or ATF2 and the DEGs analysis of liver cancer samples." (PMID 37215991, 2023). "Mechanistically, the highly activated JNK phosphorylated c-Jun and ATF2 formed a heterodimer to upregulate the expression of Galectin-1, leading to promoting cisplatin resistance in liver cancer." (PMID 37215991, 2023). "In this study, we observed that CDDP resistance of liver cancer is due to CDDP-induced activation of JNK/c-Jun-ATF2/Galectin-1." (PMID 37215991, 2023). "Next, the downstream target of JNK/c-Jun-ATF2 was identified to further clarify the mechanism of CDDP resistance in liver cancer." (PMID 37215991, 2023). "Together, these data suggested a combined regulatory mechanism for MAPK14 and ATF2 overexpression in liver cancer." (PMID 33803354, 2021). "Subsequently, MAPK14 and ATF2 were both identified as novel, direct target genes of miR-622 in liver cancer." (PMID 33803354, 2021). "MiR-622 as well as MAPK14 and ATF2 represent promising potential therapeutic targets in liver cancer." (PMID 33803354, 2021). "Combined upregulation of MAPK14 and ATF2 in liver cancer cells was also determined on the protein level applying Western blot analysis." (PMID 33803354, 2021). "In addition, the mRNA levels of Galectin-1 were significantly increased after co-transfection of C2/c-Jun and C2/ATF2 in liver cancer cells." (PMID 37215991, 2023). "Collectively, inhibition of JNK/c-Jun-ATF2 reversed CDDP resistance in liver cancer cells." (PMID 37215991, 2023). "In general, JNK/c-Jun-ATF2 upregulated the expression of Galectin-1 in liver cancer cells." (PMID 37215991, 2023). "Silencing ATF2 demonstrates anticancer effects in liver cancer." (PMID 34572296, 2021). "In conclusion, combinations of specific MAPK14- and ATF2-inhibitors might outline a synergistic therapeutic approach in (liver) cancer." (PMID 33803354, 2021). "Through promoter binding, ATF2 and endoplasmic reticulum stress induce the expression of CAP2, promoting EMT in liver cancer cells." (PMID 39633985, 2024). "JNK/c-Jun-ATF2 was found to mediate CDDP resistance through upregulating Galectin-1, which promoted DNA damage repair to enhance tumor CDDP resistance in liver cancer." (PMID 37215991, 2023).
lung adenocarcinoma (5 papers, 2020 to 2022). A carcinoma that arises from the lung and is characterized by the presence of malignant glandular epithelial cells. "Our results also show that ANKRD49 can promote the invasion and migration of A549 cells via a P38 MAPK/ATF‐2/MMPs signalling pathway in vitro and in vivo, suggesting a novel target for the remedy of lung adenocarcinoma." (PMID 35775112, 2022). "Additionally, overexpression of miR-26b-5p inhibited the expression of activating transcription factor 2 (ATF2) gene, which resulted in enhanced radiosensitivity of A549 lung adenocarcinoma cells." (PMID 34572367, 2021). "However, the biological role and mechanism of ATF2 in lung adenocarcinoma (LUAD) remains to be elucidated." (PMID 33298086, 2020).
skin tumors (5 papers, 2010 to 2020). "Similarly, the deletion of ATF2 in keratinocytes upregulated of β-catenin and downregulated of Notch consequently facilitated skin tumor formation." (PMID 27377902, 2016). "Notably, cytosolic ATF2 is primarily seen in non-malignant skin tumors." (PMID 21203491, 2010).
synovial sarcoma (5 papers, 2016 to 2020). "Several pathways have been implicated in synovial sarcoma, including altered ATF2-mediated transcription, aberrant cell cycle inhibition and modulation of SOX2 expression." (PMID 27391784, 2016). "Dysregulation of ATF2 has been reported in cancer development including synovial sarcomas, as well as in prostate and head and neck squamous cancers." (PMID 32299063, 2020). "In accordance with this, expression of Atf2 and Tle1 was increased, while that of Egr1 was suppressed in mouse synovial sarcoma." (PMID 32019274, 2020). "HDAC inhibitors have been shown to disrupt the SS18-SSX/TLE1/ATF2 protein complex, providing an explanation for the sensitivity of synovial sarcoma cells to HDAC inhibition." (PMID 28056055, 2017). "When this association is disrupted by specific knockdown of TLE1, ATF2 or SS18-SSX, synovial sarcoma cell lines undergo apoptosis, indicating this complex association is important for tumor cell survival." (PMID 28056055, 2017). "When this association is disrupted by specific knockdown of TLE1, ATF2 or SS18-SSX, synovial sarcoma cell lines are observed to undergo apoptosis, indicating this complex association is important for tumor cell survival." (PMID 27120803, 2016). "Chromatin immunoprecipitation revealed a decrease in HDAC1 and H3K23me3 at the EGR1 promoter, a known target for repression by the SS18-SSX/TLE1/ATF2 complex consistent with a disruption of the biologic effects on SS18-SSX target genes in synovial sarcoma." (PMID 27120803, 2016). "Upregulation of ATF2 and TLE1 is important in the development of human synovial sarcoma and recruitment of TLE1 to the ATF2 binding locus downregulates expression of the tumor suppressor EGR1." (PMID 32019274, 2020). "The SS18-SSX/TLE1/ATF2 protein complex has been shown to be disrupted following treatment with HDAC inhibitors, providing an explanation for the sensitivity of synovial sarcoma cells to HDAC inhibition." (PMID 27120803, 2016).
thyroid cancer (5 papers, 2020 to 2025). "Camptothecin is a DNA topoisomerase I inhibitor that blocks DNA synthesis and down-regulates THBS1 expression in human thyroid carcinoma FTC-133 cells through the JNK/ATF-2 pathway." (PMID 33746571, 2021). "TCGA database analysis revealed that ATF2 was downregulated in thyroid cancer tissue and that there was a positive correlation between ATF2 and GAS8-AS1 expression in PTC tissue." (PMID 33230459, 2020). "We previously reported that Dox-induced apoptosis of human thyroid carcinoma FTC-133 cells via JNK/ATF-2 activation." (PMID 33365267, 2020).
Cerebral ischemia (4 papers, 2018 to 2025). Restriction of arterial blood supply to the brain associated with insufficient oxygenation to support the metabolic requirements of the tissue. "Moreover, PINK1-AS can also regulate ATF2 by sponging microRNA-203, thereby exacerbating the damage caused by oxidative stress following cerebral ischemia/reperfusion." (PMID 41299664, 2025). "We have also characterized the regulatory role of PKCε in nucleocytoplasmic trafficking of ATF2 after global cerebral ischemia." (PMID 30497386, 2018). "Our results suggest that the PKCε–ATF2 signaling pathway is involved in the regulation of neurodegeneration in the hippocampus after cerebral ischemia." (PMID 30497386, 2018). "Our data support the hypothesis that PKCε phosphorylation regulates ATF2 subcellular translocation and neurodegeneration after cerebral ischemia." (PMID 30497386, 2018). "Immunohistochemical detection of ATF2 protein supports the Western blot finding that ATF2 was gradually exported from nucleus to the mitochondria of hippocampal neurons in response to cerebral ischemia." (PMID 30497386, 2018).
Insulin resistance (4 papers, 2013 to 2021). Increased resistance towards insulin, that is, diminished effectiveness of insulin in reducing blood glucose levels. "Improper activation of ATF2 target genes and ATF2 itself under conditions of insulin resistance can contribute to the development of type II diabetes mellitus." (PMID 32993798, 2020). "Other ATF2 target genes BDNF downregulation and PEA15 upregulation are also linked to the development of insulin resistance under glucose stimulation, pathophysiology of type II diabetes mellitus." (PMID 32993798, 2020). "Some ATF2 target genes, for example, BDNF and PEA15, are also linked to the development of insulin resistance under glucose stimulation." (PMID 32993798, 2020).
osteoarthritis (4 papers, 2013 to 2025). A noninflammatory degenerative joint disease occurring chiefly in older persons, characterized by degeneration of the articular cartilage, hypertrophy of bone at the margins and changes in the synovial membrane. "Differences between treatments may be primarily attributed to metabolic regulators such as Pparg and Ppara as well as Atf1, and Atf2, which have been reported as being selectively under-expressed in RA synovial extracts even when compared to osteoarthritis (OA) controls." (PMID 31071076, 2019).
osteosarcoma (4 papers, 2016 to 2026). A usually aggressive malignant bone-forming mesenchymal neoplasm, predominantly affecting adolescents and young adults. "In osteosarcoma specimens, qPCR analysis showed positive co-expression of β-catenin with KIF18B and ATF2 relative to that in adjacent tissues." (PMID 32587775, 2020). "KIF18B regulated β-catenin expression at the transcriptional level by controlling nuclear aggregation of ATF2 and at the post-transcriptional level by interacting with the adenomatous polyposis coli (APC) tumor suppressor gene in osteosarcoma cells." (PMID 32587775, 2020). "In this study, we demonstrated that miR-193a-3p and miR-193a-5p suppress the metastasis of human osteosarcoma cells by repressing Rab27B and SRR expression, through suppressing the TGFβ, Myc/Max and ATF2/ATF3/ATF4 signaling pathways." (PMID 26913720, 2016). "In addition, PBB12 interferes with the Kruppel-like factor 4 (KLF4)/hsa-miR-204-5p/activating transcription factor 2 (ATF2) pathway and affects the proliferation and invasion of osteosarcoma cells." (PMID 34141614, 2021).
ovarian carcinoma (4 papers, 2019 to 2023). A malignant neoplasm originating from the surface ovarian epithelium. "In addition, proteomics analysis of ovarian cancer exosomes revealed activating transcription factor 2 (ATF2) and metastasis-associated protein 1 (MTA1) as exosome-derived proteins that upregulate angiogenesis." (PMID 37222464, 2023). "Activating transcription factor 2 (ATF2), metastasis-associated protein 1 (MTA1) and CD147 are included in ovarian cancer-derived exosomes that induce angiogenesis and vascular permeability." (PMID 32230983, 2020). "At the molecular level, proteomics have revealed activating transcription factor 2 (ATF2) and metastasis-associated protein 1 (MTA1) housed within ovarian cancer exosomes to upregulate angiogenesis." (PMID 31409361, 2019). "Furthermore, proteomic analysis revealed metastasis-associated protein 1 (MTA1), activating transcription factor 2 (ATF2), and E-cadherin (sE-cad) housed within ovarian cancer exosomes as being involved in upregulating angiogenesis." (PMID 33228245, 2020).
renal cell carcinoma (4 papers, 2016 to 2024). "miR-451 enhances drug resistance in renal cell carcinoma by targeting the expression of ATF-2." (PMID 35692887, 2022). "However, the role of ATF2 in renal cell carcinoma (RCC) remains unclear." (PMID 27377902, 2016).
rheumatoid arthritis (4 papers, 2017 to 2025). A chronic, systemic autoimmune disorder characterized by inflammation in the synovial membranes and articular surfaces. "Rheumatoid arthritis synovial fibroblasts were treated with RANTES/CCL5 for 5, 15, and 30 min and the expression of p-c-Jun and p-ATF-2 was determined in the nuclear extracts." (PMID 29093715, 2017).
asthma (3 papers, 2014 to 2023). "In our current study, we used an OVA-stimulated murine asthma model to demonstrate the in vivo importance of ATF2 in the therapeutic potency of MSCs, particularly toward airway inflammation, which is an important pathophysiological feature of asthma." (PMID 36765266, 2023). "Therefore, for determination of the mode of action of MSC therapies in asthma, further studies are required to investigate which mediators could be affected by ATF2." (PMID 36765266, 2023). "In summary, this study demonstrates that ATF2 mediates GSH dynamics and the related functional and therapeutic ability of MSCs to alleviate inflammatory responses in an experimental asthma model." (PMID 36765266, 2023). "Consistently, activation of ATF2 by overexpression or the AA2G-based priming procedure enhanced the core functions of MSCs, improving the in vivo therapeutic efficacy of MSCs for treating asthma." (PMID 36765266, 2023).